IL2 (interleukin 2)
Diseases named in the same sentence as IL2 in open-access papers (continued):
Sharing a sentence is not in itself a finding about the gene and the disease.
tumor (continued). "The IL-2Rβ portion is attached via a cleavable linker, allowing IL-2 activity to be restricted until cleavage occurs in the tumor microenvironment." (PMID 34790830, 2021). "The resected tumor is then dissociated enzymatically and cultured in medium containing IL-2 for a period of two weeks, resulting in the proliferation of TILs." (PMID 34885176, 2021). "Recent studies have reported hypoxia-induced impairment of NK cell tumor cytotoxicity against multiple myeloma to be restored by pre-activation of IL-2 ex vivo." (PMID 33920906, 2021). "The original report showed that PEG-IL2 maintained its biological function and was more potent at controlling tumor growth compared to IL-2." (PMID 34790830, 2021). "Variability has also been observed with different linker lengths and sequences attaching IL-12 and IL-2, with specific linkers enhancing tumor localization and retention." (PMID 33803078, 2021). "IFN-γ and IL-2 promote the proliferation and differentiation of cytotoxic T lymphocytes and enhance the anti-tumor immune response, while TNF-α induces the apoptosis of target cells and contributes to the anti-tumor function." (PMID 35046962, 2021). "The anti-tumor effects of IL-2 are also indirectly limited by regulatory T cells (Treg), which expand efficiently to IL-2 in vivo due to high level expression of the high affinity IL-2 receptor." (PMID 34584159, 2021). "If SIL-2R is highly expressed in serum, the cellular immunity induced by IL-2 will be inhibited, resulting in the decline of immune function and thereby accelerating the infiltration and proliferation of tumor cells." (PMID 34422049, 2021). "nTemra cells showed lower proportion of DP phenotype than tilTemra cells, as well as lower production of IL-2 and higher production of perforin, further highlighting unique, tumor-specific phenotype and functionality of tilTemra cells." (PMID 34593620, 2021). "For example, IL-2 secreted by Th1 cells acts as a growth factor for CTLs36 and functions to recruit CTLs and retain them at the tumor site." (PMID 34262035, 2021). "Clinical responses to ACT can be modelled using transplanted PDX tumours and autologous T cells in human IL-2 transgenic NOG mice." (PMID 34503115, 2021). "TILs were extracted from tumor lesions, expanded ex vivo, and then re-infused together with interleukin-2 (IL-2) into the patient." (PMID 34209505, 2021). "The yTILs were generated by culture of excised tumour tissue collected from surgery in media supplemented with IL-2." (PMID 34503115, 2021). "NK cell–mediated anti‐tumour effect has been shown to depend on IL‐2, which is known as a survival factor of NK cells and an enhancer of the cytotoxic properties." (PMID 33733587, 2021). "Sequestration of IL-2 by Tregs via their high-affinity IL-2R receptor is an alternative mechanism by which Tregs weaken NK cell anti-tumor activities." (PMID 33995422, 2021). "The use of recombinant interleukin-2 (IL-2) as a therapeutic protein has been limited by significant toxicities despite its demonstrated ability to induce durable tumor-regression in cancer patients." (PMID 34011961, 2021). "IL-2-activated CD8+ T cells can kill tumor cells that have lostsurface antigens in a complex with MHC II and thus escaped the classical immuneresponse." (PMID 33959389, 2021). "In human studies, concurrent administration of lymphocytes raised in IL-2 and systemic IL-2 treatment resulted in complete and durable tumor regression of metastatic melanoma tumors in a subset of patients." (PMID 34140957, 2021). "Initial reports showed the successful generation of immunocytokines containing lymphotoxin, TNF, granulocyte-macrophage colony-stimulating factor (GM-CSF), and IL-2 with direct and indirect anti-tumor capabilities in vitro." (PMID 33803078, 2021). "IL2-based therapy has several significant disadvantages, particularly as it can induce anti-tumor immune response through Treg expansion." (PMID 33579033, 2021).
tumor (continued). "Our results show that pro-inflammatory cytokines (TNF-α, IL-12, IFN-γ and IL-2) increase in the spleen of tumour-bearing mice when treated with VES, whereas the anti-inflammatory cytokine IL-10 decreased transcriptionally." (PMID 34093795, 2021). "The adoptive transfer of PD-1−/− DCs increases CD8+T-cells infiltrations along with IFNγ, IL-2, perforin and GZMB secretions in the TME and thereby causing rapid tumor control." (PMID 34571899, 2021). "Another antibody that targets EDB, L19, was fused with IL-2 (L19-IL-2) and significantly improved the tumor-inhibitory efficiency of IL-2 in tumor-bearing mice." (PMID 33888679, 2021). "Strategies to stimulate anti-tumor immune responses include treatment with cytokines such as IL-2, IL-15 and IFN-α, which have been shown to augment the efficacy of immune cells in vitro and in vivo." (PMID 34681717, 2021). "It was thought to act as a crucial mediator in T cell immune responses and to play an important role in host response and tumor control, which led to test high-dose IL-2 as a novel cancer treatment in the mid 1980s." (PMID 35097027, 2021). "The anti-tumor effect was ablated when IL-2 was neutralized, signifying the dependency of IL-2 signaling for the anti-tumor activity of αCD25NIB." (PMID 34868044, 2021). "Therapeutic cytokines for tumor patients can be subclassified into the IL-1, IL-2, and IL-12 families." (PMID 33669271, 2021). "Taken together, the addition of both ASA and low-dose IL-2 to the baseline treatment elicited more IFN-γ-secreting tumor neoantigen-specific T cells." (PMID 33723260, 2021). "Some cytokines have strong anti-tumor activity, interferon-alpha and interleukin-2 are used in the treatment of malignancies." (PMID 33912192, 2021). "We showed that HuR-overexpression significantly increased cell surface PD-L1 via stabilizing CMTM6 and therefore compromised immune activation as indicated by IL-2 secretion in tumor cell-T cell co-culture system." (PMID 33649535, 2021). "In order to avoid cytokine release syndrome, membrane-bound IL-2 or IL-12 have also been expressed by tumor cells using vvDD." (PMID 34093846, 2021). "The pro-inflammatory cytokines (TNF-α, IL-12, IFN-γ and IL-2) increased in the spleen of tumour-bearing mice that had been treated with VES, whereas the anti-inflammatory cytokine IL-10 decreased transcriptionally." (PMID 34093795, 2021). "Cytokines including TNF-α, IFN-γ, IL-2, IL-6, and IL-12 were also increased in the PB and in tumour lesions of mice with P@aPDL1 and Vadimezan treatment." (PMID 33986264, 2021). "In patients, systemic administration of histamine combined with IL-2 was found to improve the efficacy of IL-2 therapy, potentially due to augmented NK cell mediated tumor cell cytotoxicity." (PMID 34063789, 2021). "Interleukin-2-(IL-2) activated tumor-infiltrating NK cells were demonstrated to have anti-tumor activity to shrink tumors in the murine tumor model." (PMID 33156394, 2021). "Production of proinflammatory cytokines, in particular interferon-gamma (IFN-γ) and interleukin-2 (IL-2), was also observed in a subset of ParvOryx01 patients’ tumor samples." (PMID 34452286, 2021). "These cells also produced higher levels of IFN-γ and IL-2, displayed elevated NFκB activity, resisted apoptosis following tumour target exposure, and were more potent at killing LAN-1 cells in vitro." (PMID 34885108, 2021). "IL-10 has been shown to have anti-tumor effects, which are enhanced when combined with IL-2; these effects can potentially be harnessed for immunotherapy." (PMID 34307161, 2021). "The mechanism of action of Ad5/3-E2F-d24-vIL2 appears more refined than its wt IL-2 armed counterpart, as evidenced by lower levels of necrosis and fewer suppressive myeloid effects at the tumor site." (PMID 34084172, 2021). "(ii) Higher CD40LG and IL-2 expression was observed in tumor tissues with genotype A_G than those with genotype A_A." (PMID 34830445, 2021).
tumor (continued). "Although IL23x-Fc was able to increase CD8+ and NK cell populations more so than the WT version, WT IL2-Fc resulted in superior tumor control." (PMID 34790830, 2021). "Nonetheless, they have been one of the first tumor types for which immunotherapy with high-dose IL-2 has proved efficient, although their responsiveness to immune checkpoint blockade remains rather low, below 30%." (PMID 33996558, 2021). "RAE-1γMCMV primed OT-1 cells produced lower amounts of IFNγ, TNFα and IL-2, showed decreased degranulation potential, while simultaneously exhibiting similar cytotoxicity against tumor cells expressing their cognate antigen." (PMID 34168650, 2021). "Our study supports the associations of tumor FOXP3/CD3 ratios, IL17A and IL2 with outcome in the rituximab era." (PMID 33648463, 2021). "Adoptive cell transfer includes harvesting T lymphocytes from an autologous source, expanding them with IL-2, identifying tumor-specific clones and reintroducing them to patients." (PMID 34277428, 2021). "Dynamic differentiation of IL-17A-expressing T cells in the tumor, due to the presence of particular mediators, such as IL-2, RANTES, or MCP-1, has been demonstrated." (PMID 34944746, 2021). "Mouse CD8+ T cells cultured in the presence of IL-2 and IL-15 (the latter promotes T cell differentiation into memory phenotypes) show greater tumor cytotoxicity than cells cultured in the presence of IL-2 alone." (PMID 32221812, 2020). "IL-2 can also induce PBMC or tumor infiltrating lymphocytes (TIL) into lymphokine-activated killer cells in vitro (LAK)." (PMID 32425919, 2020). "It is known that IL2 expand peripheral blood and tumor infiltrating T lymphocytes in vitro and in vivo." (PMID 33613510, 2020). "Several groups have delivered viruses using autologous cells, including mesenchymal stem cells (MSCs), CD14+-derived monocytes and irradiated tumor cells, interleukin-2 (IL-2)-expanded T cells." (PMID 33473255, 2020). "While the half-life extension of IL2 has been addressed by PEGylation and albumin-fusion, selective tumor accumulation has generally been achieved by fusion to antibodies forming “immunocytokines”." (PMID 33216834, 2020). "We next evaluated multifunctional CD4+ and CD8+ T cells capable of simultaneously producing multiple effector Th1 cytokines and cytotoxic markers (IFN-γ, TNF-α, IL-2, and CD107a) because these cell types are strong effectors in tumor environments." (PMID 32486094, 2020). "In the 4T1 tumor model, both IL-2 immunotherapies only mildly affected the growth of the primary tumor." (PMID 33353953, 2020). "The aim of these investigations was mainly to improve immune responses against tumors by IL-2-induced activation of tumor-infiltrating T cells." (PMID 32917054, 2020). "Taken together, it is reasonable to assume that iron impairs the anti-tumor effects of anti-PD-L1 antibodies and of IL-2/doxorubicin immunochemotherapy mainly by impairing CD8+ T cell functions." (PMID 33344239, 2020). "Evaluating data from a cohort of patients treated with high doses of IL-2, it was found that when the higher-affinity genotypes for FCGR2A, FCGR3A, and FCGR2C were considered together, they were associated with increased tumor shrinkage and prolonged survival." (PMID 32013092, 2020). "Mechanistic investigations into tumor targeted IL2 based treatments have indicated that immunological responses are correlated with an increased intratumoral presence of NK and CD8+ T cells." (PMID 33216834, 2020). "The functions of T cells were measured by quantifying the secretion of IFN‐γ and IL‐2, and by testing their ability to kill tumor cells with the release of LDH." (PMID 32157792, 2020). "Proinflammatory cytokines IL-1 and IL-2 have been shown to mediate neuroendocrine differentiation in tumor cells and gastrointestinal hormone synthesis and secretion, respectively." (PMID 32156252, 2020).
tumor (continued). "Treg cells in the tumour microenvironment have been shown to restrain the IL-2-dependent acquisition of cytotoxic functions by CD4+ T cells, impeding anti-tumour immunity." (PMID 32290500, 2020). "A durable complete regression in WEHI-164 tumor bearing mice was observed in mice treated with the combination of IL2 therapeutics with PD-1 blockade." (PMID 33110477, 2020). "We previously demonstrated clinical safety of the tumour-selective immunocytokine L19-IL2, consisting of the anti-ED-B scFv L19 antibody coupled to IL2, combined with stereotactic ablative radiotherapy (SABR)." (PMID 32539805, 2020). "This pathology analysis confirms that the IL2 fusion toxin has efficacy in depletion of human CD25+CCR4+ tumor cells." (PMID 32107846, 2020). "For example, it shows an antagonistic behaviour with anti-IL2, anti-Treg and NK infusion, because the predicted tumor inhibition of these treatments, tested as single drugs, is higher than the one obtained by combining them with the vaccine." (PMID 32493951, 2020). "In summary, this paper shows that OAd.TNFa-IL2 adenovirus virotherapy affects the tumor microenvironment through DAMP and PAMP release and subsequent activation of sensors, such as AIM2." (PMID 32225009, 2020). "This knowledge led us to evaluate the concentration of Th-1 (IFN-γ, IL-2) and Th-2 (IL-10, IL-4) serum cytokines in M-406 bearing CBi/L mice, in the different stages of tumor immunoediting." (PMID 33312693, 2020). "It was interesting that the proliferation rate of tumor cells in co-culture with hADSCs-IL2 was significantly lower in the first 72 h, compared with native hADSCs and hADSCs-BFP." (PMID 32560387, 2020). "Compared with single hormone therapy, a combination of hormone therapy and interleukin-2, interleukin-12 and interferons presented a better anti-tumor effect via synergism with antiestrogens." (PMID 32226776, 2020). "The higher expression levels of IFN-γ and IL-2 and the lower expression levels of IL-4 in the tumor tissue of DTSP-treated mice suggest that a Th1 immune response but not a Th2 immune response was activated by DTSP treatment." (PMID 32903495, 2020). "Three of the IL-2-dependent non-leukemic/normal T-cell line cells transformed into IL-2-independent tumor-producing cancer cells in vitro, along with three IL-2-independent leukemic T-cell lines." (PMID 32210945, 2020). "Local injection of IL2 in the tumor site induce disruption of tumor vessels only, science tumor blood vessels are more vulnerable than normal blood vessels to the actions of IL2." (PMID 32560387, 2020). "In a phase I clinical trial, the safety, tolerability and feasibility of ex vivo TKD/IL-2-stimulated autologous NK cells were proven in 12 patients with advanced tumor stages (colorectal cancer, n = 11; NSCLC, n = 1)." (PMID 32443761, 2020). "It remains to be fully elucidated why hADSCs-IL2 CM increases the proliferation of SH-SY5Y tumor cells, yet the physical presence of hADSCs-IL2 in co-culture has a negative effect on tumor cell viability." (PMID 32560387, 2020). "A major benefit of intralesional IL2 is the mitigation of the undesirable and often severe side effect profile of high-dose systemic IL2 while achieving high doses of IL2 at the tumor site." (PMID 32455916, 2020). "Nevertheless, coupling IL2 to a tumour specific antibody, like L19, reduces the IL2 concentration in blood and increases the concentration in the tumour, resulting in only low grade toxicity." (PMID 32539805, 2020). "Combined use of IL-2 with 1619 BiKE reduced the significant differences in the tumor growth and survival between the 2 treatment groups (1619 BiKE vs. 161519 TriKE)." (PMID 33299651, 2020).
tumor (continued). "The IL2 fusion toxin group had less hepatomegaly with fewer tumor nodules when compared with the C21 IT control group." (PMID 32107846, 2020). "ACT + NKTR-214 led to significant tumor growth inhibition with less frequent dosing in the aggressive B16-F10 model compared to ACT + IL-2 or ACT + vehicle." (PMID 32005809, 2020). "The result claimed that IL7 and IL21 were superior to IL2 and IL15 in enhancing tumor eradication, although IL2 and IL15 established increased effector functions." (PMID 33381115, 2020). "Changes in gut microbiome lead to changes in metabolic level, which affect the expression of immune-related cytokines IFN-γ and IL-2 in the tumor microenvironment, resulting in a different therapeutic effect of PD-1 antibody." (PMID 32425919, 2020). "Limitations for use of IL-2 for immunotherapy deal with the fact that IL-2 exhibits very heterogeneous variability of success due to the effect of the tumor burden, prior to therapy administration." (PMID 32354198, 2020). "Briefly, our first proposal would be extracting naïve T lymphocytes and tumor cells from the patient, and co-cultivate them in the presence of cytokines to activate cytotoxic T-cell response: i.e., IL-2, INF-α and γ, and TNF-α." (PMID 33276556, 2020). "Il-2 is known as a promotor of tumor eradication, and attempts to use Il-2 in anticancer treatment have been underway for a long time." (PMID 32422889, 2020). "These include cytokines such as IFNγ, IL-12, IL-2 and chemokines such as CXCR3 and CCR5 that are associated with tumour trafficking and stimulate cytotoxic functions." (PMID 32610601, 2020). "Overall, these gene expression changes indicate that OAd.TNFa-IL2 induces favorable changes in the tumor by affecting both the innate response through the infected cells and the adaptive immune system." (PMID 32225009, 2020). "For instance, adoptive telomerase-specific T cells obtained from peptide-immunized donor mice and stimulated with either IL-2, IL-15, APCs or allogeneic DCs, significantly slowed tumor growth and metastasis." (PMID 35582441, 2020). "While the Thy1.1/Tregs ratio was two-fold higher in spleen after ACT + NKTR-214 compared to ACT + IL-2 at day 7 and 14, this ratio was 4 and 11-fold higher in tumor, respectively." (PMID 32005809, 2020). "Meanwhile, the ELISPOT results indicated that IFN-γ and IL-2 produced splenic and tumor infiltrating lymphocytes were significantly increased." (PMID 33643911, 2020). "While infection with the OV can lead to tumor destruction as previously discussed, the addition of IL2 and TNF-alpha increases the immunogenicity of the therapy." (PMID 33053757, 2020). "MRI results revealed that as compared to the initial tumor size before treatment, tumor size was significantly reduced in the group intracranially injected with IL-2/HSP70-treated NK cells." (PMID 32218162, 2020). "The toxicity profile of systemic IL-2 gene therapy can be improved by transcriptional targeting of IL-2 to the tumor to ensure specific expression of the IL-2 gene within the tumor." (PMID 32917034, 2020). "Kynurenines inhibit proliferation, anti-tumor activity, production of IL2 and INFγ and induce CAR T-cell apoptosis." (PMID 33374128, 2020). "Injection of tumor nodules with rAV/Ii-RGC and rAV/CIITA/IFN-γ, associated with a suboptimal dose of rAV/IL-2 induced a potent antitumor immune response." (PMID 32079263, 2020). "Immature DCs stimulated by tumor antigen is activated to induce synthesis of cells and secretion of cytokines including interleukin-2 (IL-2), Tumor necrosis factor-α (TNF-α), interferon-β (IFN-β)." (PMID 33324558, 2020). "We did not observe differences in expansion rate or Vγ9Vδ2 T cell purity between the conditions; however, IL-2/IL-15-expanded Vγ9Vδ2 T cells displayed enhanced cytotoxicity against tumor cells, also in hypoxia." (PMID 32983105, 2020).